SDC1 (syndecan 1)
Diseases named in the same sentence as SDC1 in open-access papers (continued):
Sharing a sentence is not in itself a finding about the gene and the disease.
brain injury (2 papers, 2018 to 2021). Acute and chronic (see also brain INJURIES, CHRONIC) injuries to the brain, including the cerebral hemispheres, CEREBELLUM, and brain STEM. "Recently, in a multicenter RCT of 285 patients with moderate to severe traumatic brain injury, patients who received TXA (2 g) within 2 h of trauma exhibited lower syndecan-1 concentrations compared to the control group." (PMID 33915859, 2021).
brain tumor (2 papers, 2023 to 2024). "Next, we evaluate whether the high expressions of collagen type I receptors (ITGAV, ITGB8, SDC1, SDC4, and CD44) in tumor tissues, i.e., tumor receptors, are related with the prognosis of patients with brain tumor." (PMID 37479733, 2023).
breast lobular carcinoma (2 papers, 2018 to 2019). An adenocarcinoma of the breast arising from the lobules. "In this study, the lobular carcinomas demonstrated a positive correlation between the stromal Sdc1 expression and histological grade (P = 0.014)." (PMID 30151336, 2018).
cervical tumors (2 papers, 2020 to 2022). "In 26/55 (47%) cervical tumors, abnormal syndecan-1 localization was found in the stroma, most probably due to aberrant expression of this proteoglycan by stromal fibroblasts." (PMID 32388727, 2020). "Immunohistochemical analysis of cervix tumor tissues showed that the cell surface Sdc-1 expression was higher on stromal fibroblasts than in cancer cells and that patients with high cell surface Sdc-1 expression had significantly better survival." (PMID 35155241, 2022).
chronic hepatitis C (2 papers, 2019 to 2021). "Considering these findings, of equal importance, may also be the utilization of syndecan-1 in the monitoring of therapeutic effectiveness in patients with chronic hepatitis C who receive the new interferon-free therapies." (PMID 31815014, 2019).
chronic lung disease (2 papers, 2021). According to the definitions of the American and British Thoracic Societies, including pulmonary functional tests, X-rays, and CT scans for items such as fibrosis, bronchiectasis, bullae, emphysema, nodular or lymphomatous abnormalities. "One should be cautious in administering glucocorticoids in chronic lung disease because of their property of increasing the expression of SDC1 and PA binding to the airway epithelium." (PMID 34790176, 2021). "Some of these genes, such as VAMP3, LGR5, PER3, and SDC1, were found to be involved in the different physiological functions of lung and chronic lung disease." (PMID 33407823, 2021).
coeliac disease (2 papers, 2014 to 2019). "In contrast to its GAG side chains, syndecan-1 core protein expression was maintained on enterocyte basolateral membrane in coeliac disease, with staining intensity similar to normal small bowel." (PMID 25198673, 2014). "Matrix expansion, through syndecan-1+ cell recruitment and lamina propria GAG increase, underpins villous atrophy in coeliac disease." (PMID 25198673, 2014).
colorectal adenocarcinoma (2 papers, 2008 to 2019). The most common type of colorectal carcinoma. "Loss of epithelial syndecan-1 has been reported in human colorectal adenocarcinomas, but whether this has prognostic significance remains undecided." (PMID 18590537, 2008).
colorectal tumor (2 papers, 2015 to 2017). "Taken together, these studies indicate that SDC1 expression may be a useful biomarker for evaluating the stage and grade of colorectal tumors." (PMID 26293675, 2015). "The lack of consistency between studies may be related to patient selection or methodological differences, and therefore larger studies are needed to further evaluate the prognostic impact of SDC1 in patients with colorectal tumors." (PMID 26293675, 2015).
congenital heart defects (2 papers, 2024 to 2026). "High serum levels of SDC1 were observed in the acute perioperative period after the repair of congenital heart defects." (PMID 38791454, 2024).
diabetic retinopathy (2 papers, 2025). "Previous studies have demonstrated that inhibition of MMPs in retinal endothelial cells can prevent the loss of syndecan-1 under hyperglycemic conditions, implicating MMPs in endothelial glycocalyx damage in diabetic retinopathy and other vascular diseases." (PMID 40981101, 2025). "Loss of syndecan-1 has been implicated in various retinal vascular disorders, including diabetic retinopathy, hypertensive retinopathy, and METH-induced retinopathy." (PMID 40981101, 2025). "In pathological conditions such as tumor angiogenesis, diabetic retinopathy, and ischemia, dysregulation of syndecan-1 may lead to aberrant endothelial migration and abnormal vascular remodeling, contributing to disease progression." (PMID 40981101, 2025).
gingivitis (2 papers, 2021). A disorder involving inflammation of the gums; may affect surrounding and supporting structures of the teeth. "However, there are currently conflicting reports on the impact of gingivitis on the content of gingival epithelial proteoglycans, such as syndecan-1." (PMID 34821180, 2021).
Glomerular sclerosis (2 papers, 2020 to 2022). Accumulation of scar tissue within the glomerulus. "It is worthwhile to mention that serum syndecan-1 levels at 8 weeks are strongly positively associated with TC, LDLc, and HDLc levels, but also with glomerulosclerosis." (PMID 35345850, 2022). "So, these data in human renal transplant recipients are in line with our current positive association of plasma syndecan-1 with glomerulosclerosis." (PMID 35345850, 2022). "However, glomerulosclerosis scores were significantly positively associated with serum syndecan-1 levels (r = 0.53, p = 0.021) and negatively associated with creatinine clearance (r = −0.4, p = 0.049, respectively)." (PMID 35345850, 2022). "Combining all groups, increased syndecan-1 shedding was associated with TC (r = 0.5; p = 0.03) and glomerulosclerosis (r = 0.53; p = 0.021), whereas the non-HDLc/HDLc ratio was associated with the neo-intimal score in the transplanted kidneys (r = 0.65; p < 0.001)." (PMID 35345850, 2022). "Heparin(oids) treatment did not influence serum total cholesterol (TC), plasma syndecan-1 and PCSK9 levels, creatinine clearance, proteinuria, glomerulosclerosis, and arterial neo-intima formation, 8 weeks after transplantation." (PMID 35345850, 2022).
hemorrhage (2 papers, 2020 to 2023). Loss of blood from the vascular compartment to the exterior or into nonvascular body space as a result of rupture or severance of the blood vessels. "Further, hypoxia/reoxygenation (H/R), our in vitro hemorrhage model, increased miR-19b expression in human lung microvascular endothelial cells, leading to a decrease in syndecan-1 mRNA and protein." (PMID 32978505, 2020).
infarct (2 papers, 2019 to 2024). "The strongest association was found between the blood levels of syndecan-1 and adrenaline, both were independently associated with long-term mortality in patients with cardiogenic shock following infarction." (PMID 31815014, 2019).
keloid (2 papers, 2022 to 2025). An irregularly shaped, elevated mark on the skin caused by deposits of excessive amounts of collagen during wound healing. "Elevated SDC-1 in fibrotic tissues such as keloids further suggests its role in driving ECM overproduction through TGF-β/Smad and MAPK pathways." (PMID 41226609, 2025). "Interestingly, SDC-1 is upregulated in keloid tissues and fibroblasts, where its expression correlates with increased levels of ECM proteins such as α-SMA, fibronectin, pro-collagen I, and collagen III." (PMID 41226609, 2025). "-SDC-1 is induced in keloid tissues/fibroblasts, driving ECM accumulation via TGFβ1/Smad and MAPK." (PMID 41226609, 2025).
Lewis lung carcinoma (2 papers, 2019 to 2022). "In a recent study, the authors found that SCGB3A2, worked as a chaperone, directly interacted with syndecan-1 (SDC1) to facilitate the delivery of lipopolysaccharide (LPS) into the cytosol and stimulated pyroptosis in Lewis lung carcinoma (LLC) cells via up-regulating the caspase-11/NLRP3 pathway." (PMID 31616642, 2019).
Listeria monocytogenes infection (2 papers, 2020 to 2025). "Regardless, these data confirm that neutropenia significantly increases the susceptibility of Sdc1-/- mice to listeriosis, and further demonstrate that neutrophils are the primary cellular target of Sdc1." (PMID 32453780, 2020). "This phenotype is not seen in Sdc3-/- or Sdc4-/- mice, indicating that ablation of Sdc1 causes a specific gain of function that enables mice to resist listeriosis." (PMID 32453780, 2020). "We therefore examined if enhanced neutrophil responses mediate the decreased susceptibility of Sdc1-/- mice to listeriosis by testing the effects of neutralizing antibodies against CXCR2 or C5aR." (PMID 32453780, 2020). "We next examined if the absence of Sdc1 ectodomains underlies the decreased susceptibility of Sdc1-/- mice to listeriosis by injecting purified Sdc1 ectodomains into Sdc1-/- mice at 6 h pi, a time point where Lm infection-induced Sdc1 shedding is maximal in Wt mice." (PMID 32453780, 2020). "SDC1 promotes Listeria monocytogenes infection, inhibiting the formation of neutrophil extracellular traps that would induce its clearance, while L. monocytogenes induces SDC1 shedding to disrupt this host defense." (PMID 41440381, 2025). "We examined if Sdc1 promotes listeriosis by inhibiting host defense mechanisms because our results suggested that Sdc1 interferes with the clearance of bacteria after they have disseminated to hepatic tissues." (PMID 32453780, 2020). "Subsequent studies were performed with the i.v. model of listeriosis because our data indicated that Sdc1 promotes Lm pathogenesis after the onset of systemic infection." (PMID 32453780, 2020). "To figure out how Sdc1 inhibits neutrophils to promote listeriosis, we next examined if there are differences in the number of neutrophils recruited to Wt and Sdc1-/- livers." (PMID 32453780, 2020). "We demonstrate here that Sdc1 is a critical host factor that promotes listeriosis." (PMID 32453780, 2020).
nasal polyps (2 papers, 2019 to 2024). "On the contrary, the expression of Sdc-1 is positively correlated with that of IL-17 in nasal epithelial cells, glandular epithelial cells, and inflammatory cells of nasal polyps." (PMID 31145753, 2019).
nasopharyngeal carcinoma (2 papers, 2012 to 2015). A carcinoma arising from the nasopharyngeal epithelium. "An analysis of SDC1 and c-Met in samples from nasopharyngeal carcinoma patients by immunohistochemical staining indicated that high coexpression of c-Met and SDC1 was adversely correlated with patient survival." (PMID 26293675, 2015).
neuroendocrine tumor (2 papers, 2019 to 2021).
neutropenia (2 papers, 2020). A decrease in the number of neutrophils found in the blood. "Furthermore, neutrophil immunodepletion significantly increased the overall corneal bacterial burden in both Wt and Sdc1−/− mice, but induced neutropenia did not affect the significant difference in S. pneumoniae virulence seen in Wt and Sdc1−/− corneas." (PMID 33293379, 2020).
oral squamous cell carcinoma (2 papers, 2015 to 2023). "SDC1, the only PG for which there is some documentation in oral squamous cell carcinoma, seems to be associated with the differentiation status of the tumour cells." (PMID 25935541, 2015).
ovarian tumor (2 papers, 2015 to 2024). "In this context, CD138 or Syndecan 1, a transmembrane receptor belonging to the heparan sulfate group overexpressed in ovarian tumors compared to healthy ovarian tissue, regardless of their status of chemoresistance or hormonal sensitivity, could be a good target candidate." (PMID 26734610, 2015).
pregnancy diseases (2 papers, 2015 to 2017). "Based on these findings we hypothesize that Sdc-1 is a marker for implantation competence of the decidualized endometrium in women with unexplained implantation failure or pregnancy-disorders based on an insufficient implantation and angiogenesis." (PMID 28293067, 2017). "The impact of Syndecan-1 in attenuating the apoptotic signal is particularly interesting in the light of an already described influence on pregnancy disorders and therefore might provide a useful clinical tool in the future to prevent pregnancy complications provoked by inadequate implantation." (PMID 25830352, 2015).
psoriatic arthritis (2 papers, 2008 to 2024). Joint inflammation associated with psoriasis. "Syndecan-1 was present in the mononuclear infiltrates of synovia from patients with rheumatoid and psoriatic arthritis where it was expressed by plasma cells." (PMID 17545191, 2008). "Syndecan-1 expression was noted in the mononuclear infiltrates of synovial tissue from RA patients and patients with psoriatic arthritis, but there are no studies that analyse the expressions of syndecan-1 and syndecan-4 in the synovium of patients with hip OA." (PMID 38674142, 2024).
renal dysfunction (2 papers, 2020 to 2021). "Besides coagulation failure, renal dysfunction was associated with elevated circulating syndecan-1." (PMID 34557532, 2021).
stress cardiomyopathy (2 papers, 2021 to 2024). "Elevated serum SDC1 levels were also noted in patients with stress cardiomyopathy, suggesting acute GCX injury." (PMID 39175877, 2024). "The levels of syndecan-1 however are much higher in patients with AMI this likely reflects the fact that the level of injury to the vascular architecture in AMI is several folds greater than that which may occur in Takotsubo syndrome." (PMID 34095448, 2021).
thrombosis (2 papers, 2016 to 2021). "Lower ApoA1 levels were also correlated with lower platelet counts and higher syndecan-1 levels, suggesting that lower ApoA1 was associated with microvascular thrombosis and endothelial damage." (PMID 26830467, 2016).
acinic cell carcinoma (1 paper, 2021). "All nine (100%) acinic cell carcinoma cases were positive for syndecan-1 both in the stroma and cancer cells." (PMID 31540870, 2021).
acute liver failure (1 paper, 2020). Rapid deterioration of liver function causing encephalopathy and coagulopathy. "In in vivo experiment syndecan-1 attenuated acetaminophen induced acute liver failure and promoted liver repair in mice." (PMID 30826971, 2020).
acute lung injury (1 paper, 2021). A condition of lung damage that is characterized by bilateral pulmonary infiltrates (pulmonary edema) rich in neutrophils, and in the absence of clinical heart failure. "Moreover, MMP-7 has been reported to direct and confine neutrophil influx to sites of injury by mediating shedding of syndecan-1 complexes from the mucosal surface in acute lung injury." (PMID 34130757, 2021).
acute pancreatitis (1 paper, 2025). An acute inflammatory process that leads to necrosis of the pancreatic parenchyma. "In severe acute pancreatitis (SAP), inflammatory factors promote the expression of matrix metalloproteinases (MMPs) and heparinases, which degrade syndecan-1 (SDC-1) and HS, while oxidative stress disrupts HA-CD44 binding, leading to increased capillary leakage and neutrophil adhesion." (PMID 40411704, 2025).
adenoid cystic carcinoma (1 paper, 2021). A malignant tumor arising from the epithelial cells. "There was a significant difference in the stromal percentage and intensity of syndecan-1 between mucoepidermoid carcinoma and adenoid cystic carcinoma (both, p < 0.001), with higher immunoreactivity observed in the former." (PMID 31540870, 2021). "Moreover, in Warthin’s tumor, stromal syndecan-1 percentage was lower than that in adenoid cystic carcinoma (p = 0.02) and both intensity and percentage were reduced as compared to mucoepidermoid carcinoma (both, p < 0.001)." (PMID 31540870, 2021). "According to pairwise comparisons (Mann-Whitney), a significantly lower expression of syndecan-1 percentage was observed in the stroma of pleomorphic adenoma compared to adenoid cystic carcinoma (p = 0.04) and syndecan-1 intensity+percentage in mucoepidermoid carcinoma (both, p < 0.001)." (PMID 31540870, 2021).
age (1 paper, 2022). A temporal measurement of the time period elapsed since an identifiable point in the life cycle of an organism. "A study detecting syndecan-1 mRNA expression within the joints in a murine RA model showed that syndecan-1 mRNA expression levels are highest in aging knee joints, implying its role in age-related RA." (PMID 36530919, 2022).
AIDS-related lymphoma (1 paper, 2020). "SDC1 is considered to be an important marker for the diagnosis and prognosis of AIDS-related lymphoma." (PMID 32575635, 2020).
amoebiasis (1 paper, 2023). "Most of the upregulated DEPs, except Thrombospondin 1, Agrin, and Syndecan-1, involved in the ECM-receptor interaction pathway were also enriched in the amoebiasis pathway." (PMID 38069077, 2023).
asthma (1 paper, 2021). "Therefore, SDC-1 might be a novel therapeutic target in the pathologic form of airway remodeling in patients with asthma." (PMID 34671356, 2021). "However, the exact role of SDC-1 in patients with asthma remains unclear." (PMID 34671356, 2021).
atopic dermatitis (1 paper, 2025). "Using Hpse(mut)-Fc as a detection molecule, we newly detected Hpse(mut)-Fc-positive inflammatory cells in the dermis of atopic dermatitis skin and polarized HS-like structures, which were distributed together with SDC1 on the surface of the adherent U937 and THP1 cells." (PMID 41373453, 2025).
atrial fibrillation (1 paper, 2022). A disorder characterized by an electrocardiographic finding of a supraventricular arrhythmia characterized by the replacement of consistent P waves by rapid oscillations or fibrillatory waves that vary in size, shape and timing and are accompanied by an irregular ventricular response. "This analysis indicated that age, NIHSS score, history of atrial fibrillation, and high plasma syndecan-1 levels were associated with poor prognosis (p < 0.05)." (PMID 35910391, 2022).
B cell lymphopenia (1 paper, 2023). "Despite B cell lymphopenia, the patient BM contained a higher proportion of CD38high PC and expressed elevated levels of transcripts for PRDM1 (encoding BLIMP1) and SDC1 (encoding CD138) compared to two HCs." (PMID 37475856, 2023).
Behçet’s disease (1 paper, 2025). "The data obtained from the study showed that syndecan-1 levels (P < .002) and cIMT measurements (P < .015) were significantly higher in patients with Behçet’s disease compared to the healthy control group." (PMID 41578772, 2025). "In this study, it was found that serum syndecan-1 levels in patients with Behçet’s disease were significantly higher compared to healthy controls." (PMID 41578772, 2025). "In patients with Behçet’s disease, circulating syndecan-1 levels can vary at different times." (PMID 41578772, 2025). "Syndecan-1 might be elevated in Behçet’s disease to help suppress inflammation." (PMID 41578772, 2025). "This study did not examine how treatment agents affect syndecan-1 levels in patients with Behçet’s disease." (PMID 41578772, 2025). "Circulating syndecan-1 levels were higher in patients with Behçet’s disease compared to healthy controls, regardless of disease activity." (PMID 41578772, 2025). "Syndecan-1 levels (9.6 ± 8.9 vs. 5.5 ± 3.2 ng/mL, P = .002), CRP levels (3.2 [0.3-41.7] vs. 1.2 [0.3-9.6] mg/dL, P < .001), and cIMT values (0.51 ± 0.1 vs. 0.46 ± 0.1 mm, P = .015) were significantly elevated in patients with Behçet’s disease compared to the control group." (PMID 41578772, 2025).
bladder urothelial carcinoma (1 paper, 2024). "This study revealed that SDC1 could be used as a potential marker and therapeutic target for bladder urothelial carcinoma." (PMID 39238647, 2024).
brain cancer (1 paper, 2013). A primary or metastatic malignant neoplasm affecting the brain. "Upregulation of SDC1 has also been described in other tumors such as pancreatic, lung and brain cancer, and it has been postulated that this aberrant expression may play a key role in promoting growth factor signaling in cancer cells." (PMID 23327652, 2013).